TNF (tumor necrosis factor)
Diseases named in the same sentence as TNF in open-access papers (continued):
Sharing a sentence is not in itself a finding about the gene and the disease.
COVID-19 (continued). "Three key pathways (pathways in cancer, the TNF signaling pathway, and lipid and atherosclerosis) and the top six anti-COVID-19 core targets (IL-6, PPARG, MAPK3, PTGS2, ICAM1, and MAPK1) were determined to be involved in the treatment of COVID-19 with active phytomolecules of Kochiae Fructus." (PMID 35992697, 2022). "Moreover the role of microbiota in modulating host immune response, and potentially influencing disease severity also in COVID-19, is confirmed by the inverse correlation of bacterial species depleted in COVID-19 patients, with plasma concentration of several cytokines (IL10, TNF-α, CXCL10, CCL2)." (PMID 34070662, 2021). "Significant upregulation of tumor necrosis factor-α (TNF-α), interleukin-6 (IL-6), and C–C motif chemokine ligand 5 (CCL5) was observed from exposure of immortalized human hepatocytes (IHHs) to exosomes isolated from COVID-19 patient plasma compared with exosomes from healthy normal plasma." (PMID 33804769, 2021). "Pro-inflammatory cytokines such as interleukin-1 (IL-1), IL-6, IL-8, and tumor necrosis factor alpha (TNF-α) have been found to be elevated in the sera of severely and critically ill COVID-19 patients, anti-inflammatory cytokines such as IL-10 have also been found in the sera of COVID-19 patients." (PMID 34335566, 2021). "At the level of cytokines/chemokines, patients with critical COVID-19, compared to mild-moderate COVID-19 patients, showed a tendency to gain a highly correlated (and expanded) cluster of IL-1 cytokines as well as a tendency of an IFN-γ/IL-6 cluster to gain correlation with TNF-α." (PMID 34226537, 2021). "Recent research has also identified that the synergism of TNF-α and IFN-γ can trigger inflammatory cell death, tissue damage, and mortality in SARS-CoV-2 infection, and shown increased levels of IFN-γ, TNF-α, CXCL10, and CCL2 in the serum of severe COVID-19 patients." (PMID 33879239, 2021). "In agreement with this study, these findings indicated the importance of IL6, TNF and IL1B hub-high traffic genes, considered potential targets (individually or in combination) for development of effective therapeutic immunomodulation strategies to manage COVID-19 hyperinflammation." (PMID 34975885, 2021). "IL-1β, TNF-α, and IL-6 are strong inducers of plasma-membrane-located HA synthase (HAS)-2 in endothelial cells, alveolar epithelial cells, and fibroblasts, and therefore HA may also participate in the pathophysiology of COVID-19." (PMID 33401632, 2021). "Significantly upregulated genes were involved in “TNFα signaling via NF-κB”, “inflammatory responses”, and “cytokine-cytokine receptor interaction”, “IL6-JAK STAT3 signaling”, “coagulation”, “hypoxia”, which had been reported for COVID-19, while cell cycle-related pathways were downregulated." (PMID 34697287, 2021). "The exacerbated inflammation that is also found in severe COVID-19 cases is mediated especially through the uncontrolled production of pro-inflammatory cytokines such as interleukin-6 (IL-6), interleukin-8, monocyte chemoattractant protein-1 (MCP-1), and TNF-α in the cytokine release syndrome." (PMID 33968948, 2021). "The first phase 2 study aimed to evaluate whether or not early administration of TNFα inhibition by infliximab in patients with severe COVID-19 will reduce disease duration and severity (NCT04425538)." (PMID 33465050, 2021). "In addition, there were higher correlations between IL-2 and IL-4, TNF-α and IL-2, TNF-α and IL-4, TNF-α and IFN-γ, and NK cells and T cells in COVID-19 patients, and there was a higher correlation between CD3+CD4+ T cells and CD19 + T cells in cancer patients." (PMID 34712741, 2021).
COVID-19 (continued). "Moreover, the serum levels of IFN-γ, TNF-α, IL-2, IL-4 and IL-10 were not correlated with disease severity among COVID-19 patients." (PMID 34123873, 2021). "PCT, ferritin, TNF-α, and IL-1α are molecular mediators of the immune system where concentrations are altered immediately post-trauma and therefore their evaluation at admission is not reliable to predict COVID-19 outcomes in the context of trauma." (PMID 35126355, 2021). "Patients with severe COVID-19 show increased IL-2, IL-6, IL-7, granulocyte colony-stimulating factor (G-CSF), interferon-γ-inducible protein 10 (IP-10), monocyte chemoattractant protein 1 (MCP-1), macrophage inflammatory protein 1-α (MIP-1), and tumor necrosis factor-alpha (TNFα)." (PMID 35062245, 2021). "In patients with COVID-19 hospitalized in intensive care units, elevated serum levels of IL-1β, IL-7, IL10, IL-17, IL-2, IL-9, Th17, IFN-γ, GM-CSF, G-CSF, IL-8, TNF-α, MIP1B, MCP1, MIP1A, and IP10 were observed, suggesting that the relation between periodontitis and COVID-19 may be established." (PMID 34068221, 2021). "Such secondary infectious events may explain the persistently elevated TNF-α levels accompanied by increased neutrophil count in COVID-19 patients with ARDS and in non-survivors." (PMID 33845874, 2021). "This phenomenon suggested the decrease of T-cells in COVID-19 patients may be due to the negative effects of high serum concentrations of TNF-α, IL-6, IL-10 on the survival or proliferation of T-cells." (PMID 33435865, 2021). "Reports looking at peripheral blood from large numbers of COVID-19 patients have consistently documented lymphopenia (reduced lymphocyte frequency) paired with increased levels of CD14+ monocytes and inflammatory cytokines, such as IL1B, TNF-α, IFN-α, and IFN-γ." (PMID 33879239, 2021). "Further, our analysis with the 21 and seven genes (that link the diabetes pathway with COVID-19) suggests that TNF and INSR are key targets in COVID-19 patients with pre-existing diabetes, and the anti-TNF anti-INSR drugs may be repurposed in managing the COVID-19 severity in diabetic patients." (PMID 34067609, 2021). "Direct comparisons between patients with influenza and COVID-19 (including patients from both groups with acute respiratory failure) demonstrate that those with influenza had increased IFN pathway responses and reduced TNF and IL-1β responses compared to patients with COVID-19." (PMID 33575657, 2021). "Another complementary study has not only confirmed that severe COVID-19 patients display significantly higher plasma levels of IL-6, IL-10, and TNF-α than mild cases but also demonstrated a negative correlation between the plasma concentration of these cytokines and the recovery phase." (PMID 34209845, 2021). "From the results of COVID-19 clinical research, we can find CPMs can regulate the proportion of lymphocyte and leukocyte, significantly reduce the level of inflammation factors such as CRP, D-dimer, PCT, IL6, IL10, IL17, TNF-α, and IFN-γ, and increase the level of IL4." (PMID 34335247, 2021). "The correlation coefficients for TNF-α and IL-2, and TNF-α and IFN-γ were higher in the COVID-19 group than that in the cancer group, while the correlation coefficients between CD3+CD4+ T cells and CD19+ B cells were higher in the cancer group than that in the COVID-19 group." (PMID 34712741, 2021). "In a large multicentre, retrospective, cohort study involving 232 cancer patients and 519 patients without cancer, increased TNF-α and IL-6, as well as decreased lymphocytes and CD4+ T cells, were found to be risk factors for disease aggravation in patients with cancer and COVID-19." (PMID 34123873, 2021). "Whilst the levels of some cytokines (i.e., IL-6, IL-8, IP-10, TNF-α, sCD25) declined one month after the SARS-CoV-2 diagnosis, others (MIP-1β, IL-1β, MIP-1α and IFN-γ) showed higher levels at month 1 and/or 3 in patients with mild/moderate disease compared to those with severe COVID-19." (PMID 34835384, 2021).
COVID-19 (continued). "Cytokine storm, hyperinflammation, multiorgan failure, and acute respiratory distress syndrome were described in COVID-19 patients with high fever, dyspnea, lymphopenia, and high serum ferritin, D-dimers, C-reactive protein (CRP), and cytokines, including IL-1b, IL-6, and TNF-α." (PMID 34578460, 2021). "The studies have shown that Bufei Huoxue Capsule could effectively improve pulmonary fibrosis, reduce the expression of inflammatory factors such as TNF-α and IL6, promote lung tissue repair, and effectively improve the immune response, which also contributes to the recovery of COVID-19." (PMID 34335247, 2021). "Based on the biological molecular docking method, the anti-COVID-19/UCEC effect of PLB could be achieved by some of the core genes, including MAPK3, TNF, and PLAU, as PLB exerted better active cavities and binding affinity in MAPK3, TNF, and PLAU when docking." (PMID 34712201, 2021). "TNF-α has been widely used in vitro studies to elicit pro-inflammatory conditions as observed in hypertension and cardiovascular diseases, and as such, TNF-α co-treatment of endothelial cells, along with S1, was used to mimic pre-existing cardiovascular comorbidity in the setting of COVID-19." (PMID 34835015, 2021). "It is known that cytokine storm in COVID-19 consists of various, not necessarily overlapping, soluble immune mediators (SIMs) including IL-1β, IL-6, IL-8, and tumor necrosis factor-alpha (TNF-α) which could yield different predictive value." (PMID 33918563, 2021). "It has been reported that COVID-19 induces higher plasma levels of cytokines including, but not limited to, IL-6, IL-2, IL-7, IL-10, tumor necrosis factor-α (TNF-α), IFN-γ-inducible protein, etc., in ICU patients with SARS-CoV-2 infection, which refers to a cytokine storm in patients." (PMID 34880750, 2021). "In particular, macrophage chemokines, referred to as major components of the cytokine storm during COVID-19, including macrophage inflammatory protein 1-alpha (MIP1α), CTACK, RANTES, eotaxin, growth-related oncogene alpha (GRO-α), and TNF were found at significantly low levels in pregnant patients." (PMID 34458162, 2021). "TNF also promotes viral entry and dissemination since it induces adhesion molecule expression in endothelial cells and promotes VEGF generation, all of which contribute to increased permeability of the endothelial layer and thereby dissemination of SARS-CoV2 in patients with COVID-19." (PMID 35264975, 2021). "According to other studies, doxycycline may delay COVID-19 progression via anti-inflammatory activities, including regulating the NFκB pathway and inhibition of proinflammatory cytokine levels (IL-6, IL-1β, TNFα), measured during ARDS in severely ill COVID-19 patients." (PMID 34372498, 2021). "However, COVID-19-recovered older participants (n = 51) had greater antibody and T-cell responses, including IFNγ+ and IFNγ+IL-2+TNFα+-specific CD4+ T cells (p < 0.0001), as well as TNFα+-specific CD8+ T cells (p < 0.001), than COVID-19-naive older adults." (PMID 34868051, 2021). "TCs have shown great potential for the management of COVID-19 through inhibition of SARS-CoV-2–induced hyperinflammation and cytokine storm, since TCs downregulate the production of inflammatory cytokines, including interleukins (IL-6, IL-33, and IL-1β) and tumor necrosis factor (TNF)-α." (PMID 33967777, 2021). "In particular, mild COVID-19 is characterized by increase of IFN-α, IFN-γ, IL6, IL10, IL1RA [TE87, TE88, TE89], while severe disease is characterized by a downregulation of IFNα, and a parallel up-regulation of IFN-β, IFN-γ, IL6, TNF, IL10, CCL7 [TE89, TE90, TE94]." (PMID 34876157, 2021). "Clinical studies have shown elevated inflammatory cytokines, including tumor necrosis factor-alpha (TNF- α), interleukins (IL; IL2, IL6, IL7, IL8, IL9, and IL10), chemokines (CXCL10, CCL2, IP10, MCP1), and colony-stimulating factors (G-CSF, GM-CSF) in COVID-19 patients compared to a healthy person." (PMID 34513735, 2021).
COVID-19 (continued). "In fact, in critically ill COVID-19 patients, IFN-I and INF-III levels and IFN-stimulated gene responses are lower compared with other respiratory viruses, while proinflammatory cytokines, including interleukin-2 (IL-2), IL-6, and tumor necrosis factor (TNF), are increased." (PMID 34769508, 2021). "The interrelationship of immune cells in COVID-19 was intrinsically identified, whereby T cells secreting IL-2, IL-4, and IL-17A were enriched among CD28+ and CD57− cells and cells secreting perforin/granzyme B/IFN-γ/tumor necrosis factor alpha (TNF-α)-expressed markers of terminal differentiation." (PMID 34488453, 2021). "NGAL is known to be inflammation-driven, and the lack of NGAL upregulation might be attributed to a lack of renal inflammation since in COVID-19 patients the mRNA levels of renal IL-6, TNFα and MMP8 were similar to controls." (PMID 34112226, 2021). "Surprisingly, up to now, no TNFα inhibitors have been trialed for COVID-19." (PMID 33465050, 2021). "Given the vital role of cytokine storm in the pathogenesis of COVID-19, agents able to reduce the release of many cytokines involved in the initiation and progression of inflammation (such as IFN-γ, IL-6, and TNF-α) may assist in preventing the progression of the disease." (PMID 33995078, 2021). "The induction of TNF-α by SARS-CoV-2 infection and the subsequent upregulation of ACE2 and TMPRSS2 in cardiomyocytes may partially explain the high incidence of cardiac involvement in hospitalized COVID-19 patients." (PMID 34576032, 2021). "Thus, adipose IRF5 transcripts in obesity correlate positively with TNF-α, IL-1β, IL-6, CXCL8/IL-8, CXCL9/MIG, CXCL10/IP10, CCL2/MCP1, CCL5, and CCL7/MCP3, all of which can be elevated in COVID-19 “cytokine storm”; positive correlations with IL-2 and IL-12 have been reported by the same group." (PMID 33936053, 2021). "PIMS-TS children had significantly elevated levels of cytokines, IFNγ, IL-2, TNFα, IL-1α, IFNα, IFNβ, IL-6, IL-15, IL-17A, GM-CSF, IL-10, IL-33 and IL-Ra; elevated chemokines, CCL2, CCL19, CCL20 and CXCL10 and elevated VEGF, Granzyme B and PDL-1 in comparison to COVID-19, seropositive and controls." (PMID 33813138, 2021). "This study emphasizes that biologically active components of spices might alleviate the sustained pro-inflammatory condition by inhibiting the activity of tumor necrosis factor-alpha (TNF-α), interleukins (IL6, IL8), and chemokine (CCL2) known to be elevated in COVID-19." (PMID 34513735, 2021). "Those ICU admitted COVID-19 patients exhibited increased plasma levels of IL-2, IL-7, IL-10, granulocyte colony-stimulating factor, monocyte chemoattractant protein- 1, interferon-inducible protein 10, and TNF-α than the non-ICU admitted patients." (PMID 33869282, 2021). "This may also explain why TNF levels positively correlated with CHRFAM7A in controls but not in COVID-19 patients." (PMID 34088975, 2021). "TH17 cells have a major role in inducing the proinflammatory effects of cytokines (G-CSF, IL1B, IL6, and TNF) and chemokines (KC, MIP2A, IL8, IP10, MIP3A) through secretion of inerleukin-17 (IL17), thus contributing to the cytokine storm and subsequent ARDS in COVID-19 patients." (PMID 34975885, 2021). "It seems that anti-TNF-α use does not lead to a serious outcome for patients with COVID-19." (PMID 34938746, 2021). "Severely ill patients hospitalised with COVID-19 exhibit increased levels of many cytokines, including Interleukin (IL)-1β, IL-2, IL-6, IL-7, IL-8, IL-10, IL-17, granulocyte colony stimulating factor (G-CSF), monocyte chemoattractant protein 1 (MCP-1) and tumor necrosis factor (TNF)." (PMID 34205262, 2021). "Severe COVID-19 patients show a notable elevation of inflammatory cytokines such as IL-2R, IL-6, granulocyte colony-stimulating factor (GCSF), macrophage chemotactic protein-1 (MCP1), macrophage inflammatory protein (MIP)1A, TNF-α and anti-inflammatory compounds such as CRP." (PMID 32876941, 2020).
COVID-19 (continued). "However, RR estimates of COVID-19 diagnosis after propensity score matching with some of the covariates that predict receiving anti-TNFα were not substantially different than RR estimates in the unmatched sample." (PMID 33519443, 2020). "None of the COVID-19 patients had increased TNF-α production in response to LPS stimulation." (PMID 32687484, 2020). "Hence, here it is suggested that S1P analogs may block the infiltration of immune cells with inflammatory phenotype, particularly CD8+ T cells secreting TNF-α or IFN-γ, which may prevent acute lung injury during COVID-19." (PMID 32670273, 2020). "We hypothesize that TNF-α and IL-6 may contribute to the occurrence of CSS in COVID-19." (PMID 33584719, 2020). "Specially, an analysis on peripheral blood mononuclear cells from 14 patients in deteriorated condition from COVID-19 and 3 healthy controls revealed that COVID-19 patients have higher levels of both PD-1 and TIM-3 as well as remarkably elevated serum levels of IL-6, IL-10, and TNF-α." (PMID 32967229, 2020). "The secretion of TNF-α and IL-6 by CD4+ Th cells in the peripheral blood may not be the main reason for the significant increase in TNF-α and IL-6 in the peripheral blood of COVID-19 patients." (PMID 32976531, 2020). "Principle behind use: severe cases of COVID-19 are characterized by a cytokine storm defined as a sudden production of cytokines, such as IL-2, IL-7, IL-10, granulocyte colony-stimulating factor (G-CSF), MCP1, MIP-1a, and TNF-α, secondary to the upregulation of the inflammatory process in COVID-19." (PMID 32953365, 2020). "The cytokine storm landscape of COVID-19 patients was further demonstrated in a retrospective study showing higher concentrations of IL-2, IL-7, IL-10, G-CSF, C-X-C motif chemokine ligand (CXCL)-10, C-C motif chemokine ligand (CCL)-2, CCL-3, and TNF-α in the plasma of severe COVID-19 patients." (PMID 33584335, 2020). "Interestingly, plasma IP-10 concentrations decreased throughout the study interval and plasma TNF-alpha did not substantially increase from relatively low circulating values throughout the course of severe COVID-19." (PMID 33488630, 2020). "Another popular candidate, Lianhuaqingwen (LH), was shown to significantly inhibit SARS-CoV-2 replication in Vero E6 cells and markedly reduce production of pro-inflammatory cytokines (TNF-α, IL-6, CCL-2/MCP-1 and CXCL-10/IP-10), suggesting that it might be a potential option for COVID-19 treatment." (PMID 33643033, 2020). "In this regard, the release of anti-inflammatory cytokines from skeletal muscle contraction, cortisol elevations, prostaglandin E2, and soluble receptors against TNF and IL-2, and increased mobilization of immunoregulatory leukocyte subtypes may be relevant in attenuating the CRS in COVID-19." (PMID 33212762, 2020). "Interestingly, IBD patients with COVID-19 on anti-TNF-alpha therapy do not seem to fare worse than those treated with less immunosuppressive drugs and, furthermore, they seem to do better." (PMID 32824122, 2020). "In COVID-19, this cytokine storm is characterised by the increase of interleukin (IL)-2, IL-7, granulocyte-colony stimulating factor, IFN-γ, inducible protein (IP)-10, monocyte chemoattractant protein (MCP)-1, macrophage inflammatory protein (MIP) 1-α, and tumour necrosis factor (TNF)-α." (PMID 33101440, 2020). "By contrast, clinical trials of relevant IL-6, TNF, and JAK STAT inhibitors and blocking antibodies are applied to the adverse side of dysregulated IFN response, which are devised to mitigate the pathological IFN and pro-inflammatory response sustained in severe COVID-19." (PMID 33322160, 2020). "In COVID-19, the absence of secondary lymphoid follicle formation may be due to the shift from traditional follicular helper differentiation to a Th1 phenotype in response to high expression of TNF in the tissue environment." (PMID 41210940, 2025).